CASR (calcium sensing receptor)
Diseases named in the same sentence as CASR in open-access papers (continued):
Sharing a sentence is not in itself a finding about the gene and the disease.
parathyroid adenomas (30 papers, 2009 to 2026). "CaSR gene plays an important role in parathyroid adenoma development, as only a single genetic mutations has been identified, which is not confirmed by other studies." (PMID 37223014, 2023). "Actually, these data could partially explain the coexistence in a same patient of a germline CASR loss-of-function pathogenic variant and a parathyroid adenoma and the consideration of FHH-negative subjects as an atypical form of PHPT." (PMID 38214877, 2024). "The CASR gene is known to play a role in parathyroid growth; therefore, we suppose that some variants may promote both hyperplasia and parathyroid adenoma formation." (PMID 37810884, 2023). "However, a dozen cases of parathyroid adenomas associated with CASR mutations have been reported, with two families having adenoma and/or familial hyperplasia of the parathyroids with papillary microcarcinoma." (PMID 28122587, 2017). "Future studies utilizing selective microraft capture of functionally characterized parathyroid adenoma cells are likely to reveal molecular genetic features specifically associated with diminished calcium sensing even in the presence of intact CASR protein expression." (PMID 26638194, 2016). "Conversely, other germline mutations predisposing to parathyroid adenomas, such as MEN1, CASR, and FHH, are rarely implicated in PC." (PMID 41568161, 2026). "It has been proposed that over secretion of PTH in patients with PHPT is, among others, produced by an alteration of the CaSR set-point, being the immunohistochemical expression of the CaSR and CaSR mRNA expression reduced in parathyroid adenomas." (PMID 38214877, 2024). "Alongside the reduction in CaSR, the number of vitamin D receptors (VDRs) in parathyroid adenoma is also decreased." (PMID 39519190, 2024). "In this paper, we present a unique case of the co-existence of an inactivating CaSR gene mutation and PHPT due to a single-gland parathyroid adenoma." (PMID 38021951, 2023). "PHPT is most often caused by a single-gland parathyroid adenoma and FHH is the result of an inactivating mutation of the calcium-sensing receptor (CaSR) gene." (PMID 38021951, 2023). "Reduced expressions of CaSR and vitamin D (1,25- dihydroxyvitamin D3) receptor (VDR) have been implicated in aberrant calcium signaling in sporadic parathyroid adenomas indicating their mechanistic roles in parathyroid tumorigenesis." (PMID 35681135, 2022). "To test this idea, we performed calcium flux measurements in a series of primary parathyroid adenoma specimens and then probed the cells for CASR protein expression via immunofluorescence in situ on the microraft grids." (PMID 26638194, 2016). "Consistent with this idea, we have frequently observed marked intratumoral regional variations in the subcellular localization of CASR in primary parathyroid adenomas." (PMID 27537691, 2016). "Regional differences in the abundance and subcellular localization of CASR within individual parathyroid adenomas suggests that the capacity to respond to extracellular calcium stimulus would be non-uniform among tumor cells." (PMID 27537691, 2016). "These alternative modes of PTH hypersecretion revealed distinct actions of the CaSR and the VDR that may underlie the divergent secretory patterns seen in different types of parathyroid adenomas." (PMID 40492090, 2025). "Moreover, reduced expression of CASR has been demonstrated in parathyroid adenomas and, even more so, in parathyroid carcinomas with a high proliferative index." (PMID 40870022, 2025). "In addition to MEN1 and CCND1, other genes that participate in the development of parathyroid adenoma include those encoding cyclin-dependent kinase inhibitors, along with CTNNB1, EZH2, ZFX, GCM2, and CASR." (PMID 30832348, 2019).
parathyroid adenomas (continued). "However, in contrast to cases with FHH due to pathogenic variants in CASR, AP2S1, or GNA11, surgery may cure the disease (Case 3) unless hyperplastic glands or other parathyroid adenomas are missed during the first surgery in cases of MGH (Case 2)." (PMID 38130397, 2023). "CaSR, MEN1, CCND1/PRAD, CDKI, angiogenic factors like VEGF, FGF, TGFβ, and IGF1, and apoptotic factors are important genes in parathyroid adenomas pathogenesis that have been established by several studies." (PMID 37223014, 2023). "GCM2 is a parathyroid-specific transcription factor involved in parathyroid embryogenesis; during adult life, GCM2 maintains CASR expression, and downregulated GCM2 transcripts have been reported in parathyroid adenomas." (PMID 33670622, 2021). "In the series of parathyroid adenomas, coexpression of YAP1 and CASR was analyzed by immunohistochemistry (IHC)." (PMID 33670622, 2021). "Moreover, we have recently shown in dispersed cell studies that parathyroid adenomas are comprised of functionally distinct cellular subtypes that differ in their relative sensitivity to calcium stimulation despite equivalent levels of CASR expression in each population." (PMID 27537691, 2016). "Considering that both CASR and YAP1 feature as tumor suppressors in parathyroid adenomas, the induction of SOX2 expression may promote cell resting more than cell proliferation." (PMID 34199594, 2021). "In a previously reported study, a patient with a parathyroid adenoma, who had not achieved clinical remission following resection of the adenoma, was started on a CaSR agonist that subsequently alleviated the clinical symptoms." (PMID 35095753, 2021). "Unlike CDC73, other germline disorders that predispose to parathyroid adenomas, such as those involving mutations in MEN1, FHH, CASR, CGM2, are rarely, if ever, associated with parathyroid carcinoma." (PMID 31661917, 2019). "Utilizing the system's capacity to align post‐assay immunofluorescence image analysis with the individual record of each cell's functional response, we show that the presence of detectable CASR protein is not the sole determinant of calcium sensitivity in parathyroid adenoma cells." (PMID 26638194, 2016). "Our observation that CASR protein abundance alone does not dictate calcium responsiveness supports the concept of mechanistic heterogeneity in the failure of calcium sensing in parathyroid adenomas." (PMID 26638194, 2016). "studies in rats, CaSR, VDR, and RET gene evolvement in parathyroid adenoma has not been confirmed, although these are involved in hereditary disease and play significant role in parathyroid gland biological processes." (PMID 37223014, 2023).
autosomal dominant hypocalcemia (28 papers, 2010 to 2025). Autosomal dominant hypocalcemia (AD hypocalcemia) is a disorder of calcium homeostasis characterized by variable degrees of hypocalcemia with abnormally low levels of parathyroid hormone (PTH) and persistent normal or elevated calciuria. "The monogenic bone disorder Autosomal dominant hypocalcemia (ADH) type 1 is caused by heterozygous activating mutations in the calcium-sensing receptor (CASR), which increase the CASR sensitivity to extracellular ionized calcium." (PMID 35163424, 2022). "Activating mutations of the CaSR gene cause enhanced sensitivity to extracellular calcium concentration resulting in autosomal dominant hypocalcemia or Bartter-syndrome type V. Inactivating CaSR gene mutations lead to resistance to extracellular calcium." (PMID 33528764, 2021). "In particular, gain-of-function CaSR mutations result in autosomal dominant hypocalcemia (ADH) or type 5 Bartter syndrome and eight of them are clustered in loop 2 close to the two cysteines responsible for receptor homodimerization, i.e., cys129 and cys131." (PMID 31717830, 2019). "Autosomal dominant hypocalcemia (ADH) is a disorder of systemic calcium homeostasis caused by increased sensitivity of the calcium-sensing receptor (CaSR) signaling pathway to extracellular calcium (Ca2+o) concentrations." (PMID 28194447, 2017). "Autosomal dominant hypocalcemia (ADH) type 1 is caused by heterozygous activating mutations in the CASR which increase the sensitivity of the CASR to extracellular ionized calcium." (PMID 27803672, 2016). "Activating mutations of the CaSR disturb this regulatory feedback loop by lowering the calcium set-point of the CaSR and cause autosomal dominant hypocalcemia (ADH)." (PMID 25506941, 2014). "Conversely, CaSR gain-of-function mutations cause autosomal dominant hypocalcemia (ADH) or type 5 Bartter syndrome, due to activation of the receptor at concentrations of serum calcium below physiological levels leading to abnormal inhibition of PTH secretion." (PMID 24244430, 2013). "In Western cohorts, CASR gain-of-function mutations are among the most frequently reported causes of autosomal dominant hypocalcemia, whereas GCM2 mutations are relatively rare but have been described in Latin American and South Asian families, sometimes linked to founder effects." (PMID 41155848, 2025). "In humans, gain-of-function mutations of the calcium-sensing receptor (CASR) gene are the cause of autosomal dominant hypocalcemia or type 5 Bartter syndrome characterized by an abnormality of calcium metabolism with low parathyroid hormone levels and excessive renal calcium excretion." (PMID 24244430, 2013). "However, it may be that gain-of-function CaSR mutations, which cause autosomal dominant hypocalcemia (ADH), are associated with abnormalities of glucose homeostasis and not FHH-associated loss-of-function CaSR mutations." (PMID 28575322, 2017). "Autosomal dominant hypocalcemia (ADH) is a disorder of systemic calcium homeostasis, which affects the parathyroid glands and kidneys, and is caused by increased sensitivity of the calcium-sensing receptor (CaSR) to extracellular calcium (Ca2+e) concentrations." (PMID 31820785, 2020). "T888M was identified previously in a human kindred with autosomal dominant hypocalcemia (ADH) providing evidence that phosphorylation of T888 impairs 1) sustained elevations in Ca2+i and 2) CaSR-mediated suppression of PTH secretion." (PMID 36818436, 2023). "This group of inherited hypocalcemic disorders involves the autosomal dominant hypocalcemia (ADH) (ADH1 and ADH2) and Bartter-syndrome type V. Other genetic defects inactivate the calcium sensing pathway leading to resistance to extracellular ligands of CaSR." (PMID 33528764, 2021).
neonatal hyperparathyroidism (25 papers, 2007 to 2024). "Neonatal severe hyperparathyroidism (NSHPT) is a rarely occurring life-threatening disorder associated with variants in the calcium-sensing receptor (CASR) gene." (PMID 39129820, 2024). "Neonatal hyperparathyroidism (OMIM phenotype number 239200) is an AD/AR condition resulting from inactivating variants in CASR that decrease the sensitivity of CaSR to extracellular calcium." (PMID 38606357, 2024). "In stark contrast, homozygous mutations of CaSR cause neonatal severe hyperparathyroidism (NSHPT) which is associated with severe metabolic disturbances, growth retardation, and death." (PMID 35857775, 2022). "The development of neonatal hyperparathyroidism in FHH is likely modified most significantly by the parental origin of the CaSR mutation." (PMID 34659108, 2021). "Neonatal hyperparathyroidism is a rare disease caused by a homozygous inactivating mutation in the calcium sensing receptor gene." (PMID 34887979, 2021). "The parents, who presented a mild phenotype of neonatal hyperparathyroidism, were heterozygous for a CASR gene mutation." (PMID 34828426, 2021). "Hypercalcaemia disorders are related to inactivating mutations of the CASR gene either heterozygous (autosomal dominant familial benign hypercalcaemia, still named hypocalciuric hypercalcaemia syndrome type 1) or homozygous (severe neonatal hyperparathyroidism)." (PMID 28122587, 2017). "Commonly, heterozygous inactivating pathogenic variants of the CASR gene lead to FHH, whilst homozygous or compound heterozygous inactivating mutations cause severe neonatal hyperparathyroidism." (PMID 38214877, 2024). "Inactivating mutations of the CaSR can cause disorders of calcium metabolism including familial hypocalciuric hypercalcemia type 1 (FHH1) and neonatal severe hyperparathyroidism (NSHPT)." (PMID 27803671, 2016). "Milder phenotypes are summarized as neonatal hyperparathyroidism (NHPT) and refer to infants with elevated serum PTH levels and resulting bone disease, but only modest hypercalcemia, usually based on heterozygous inactivating mutations of CaSR." (PMID 34659108, 2021).
Obesity (25 papers, 2012 to 2025). Accumulation of substantial excess body fat. "In AT inflammation, higher CaSR activity is expected to further upregulate proinflammatory cytokines, likely enhancing inflammation-linked obesity disorders." (PMID 33076271, 2020). "However, recent studies have shown that CaSR can modulate a variety of cellular processes associated with inflammation and the CV system, such as AS, hypertension, vascular calcification, obesity, and myocardial infarction." (PMID 41303064, 2025). "Our subgroup analysis clearly indicated, however, that increased [Ca2+]ex-induced, CaSR mediated IL-1ß release was not limited to people with a clinically detectable inflammatory state, but was also associated with obesity in individuals with normal CRP levels." (PMID 35931812, 2022). "In the present work, we focus on human visceral AT explants to study whether CaSR expression is associated with obesity and if its activation induces autophagy in the tissue context." (PMID 33076271, 2020). "Our model indicates that CaSR could mediate the association between obesity and autophagy in AT that has been consistently documented." (PMID 33076271, 2020). "CaSR expression in visceral AT is directly associated with % body fat, and CaSR activation may contribute to obesity-related disruption in AT autophagy." (PMID 33076271, 2020). "The association between CaSR and autophagy in AT has only been recently explored, and our present findings further contribute to understanding well-known autophagy dysregulation in AT of people with obesity." (PMID 33076271, 2020). "Interestingly, we observed that CaSR mRNA in AT explants was positively correlated with %BF, which in addition to being an obesity indicator, is strongly associated with low-grade inflammation." (PMID 33076271, 2020). "Our results show that CaSR expression is associated with donors’ body fat percentage (%BF), and that CaSR activation modulates autophagy-related mRNA transcripts and proteins, suggesting that CaSR may strengthen obesity-dysregulated autophagy in AT." (PMID 33076271, 2020). "Finally, the paths from %BF to autophagy and TNF-α are not significant (gray doted lines), supporting the hypothesis that CaSR and autophagy mediate the association between obesity (%BF) and expression of TNF-α in our model." (PMID 33076271, 2020). "In AT in obesity, CaSR expression has been reported to be involved in AT inflammation, since it is upregulated on adipocytes in response to inflammatory cytokines and triggers their proinflammatory response by activating the NLRP3 inflammasome." (PMID 35931812, 2022). "Studies from our group showed that macrophages from adipose tissue of patients with obesity respond with markedly increased IL-1β release after calcium stimulation of CaSR." (PMID 36685206, 2022). "Instead, we propose that CaSR mediated signalling is relevant for the deleterious innate immune activation in obesity." (PMID 35931812, 2022). "In summary, we have shown that macrophages from people with obesity, and whole tissue cultures from visceral AT, show increased [Ca2+]ex-induced, CaSR-mediated NLRP3 inflammasome activation and IL-1ß release when compared to people who were not obese." (PMID 35931812, 2022). "Autophagy has also been shown to contribute to adipocyte dysfunction in obesity, and the CaSR seems to regulate this process by promoting the formation of the autophagosome." (PMID 36467702, 2022). "By multivariate analysis, we show that elevated CaSR mRNA expression in subjects with higher %BF is a contributing factor to obesity-related elevation of autophagy at the transcriptional level." (PMID 33076271, 2020). "There is minimal information available on the expression of gastric CaSR in obesity, with the current report showing an increase in antral CaSR mRNA expression in HFD-induced obese mice compared to controls." (PMID 32824949, 2020).